CIDEC (cell death inducing DFFA like effector c)
Diseases named in the same sentence as CIDEC in open-access papers:
CIDEC is named in the same sentence as 51 diseases in open-access papers, as found by Europe PMC text mining. Sharing a sentence is not in itself a finding about the gene and the disease. The quoted sentences say what the papers report.
Hepatic steatosis (24 papers, 2009 to 2026). Steatosis is a term used to denote lipid accumulation within hepatocytes. "Previous studies reported aggravated liver steatosis associated with increased serum TG in CIDEC-deficient, CIDEC-/-/ob/ob double-deficient, CIDEC-/-/BATless, and adipose-specific knockout mice 12-17." (PMID 36263170, 2022). "Increased hepatic CIDEC expression is observed in fatty livers of mice, alcohol-fed rats (unpublished observations) and obese patients, and hepatocyte-specific loss of CIDEC ameliorates hepatic steatosis." (PMID 32585865, 2020). "The expression of PPARG coactivator 1 alpha (Ppargc1a), which is involved in glucose and fatty acid metabolism, and cell death-inducing DFFA-like effector c (Fsp27), a lipid droplet protein involved in hepatic steatosis, were also significantly reduced." (PMID 39956880, 2025). "CIDEC expression is 10-fold increase in the liver of these animals and liver-specific CIDEC overexpression has been shown to induce liver steatosis." (PMID 35250856, 2022). "In order to validate the association of LDAP expression and hepatic steatosis observed in animal models, we further measured the protein expression of FSP27/CIDEC and LSDP5 in human livers." (PMID 26770990, 2016). "The lipid droplet-associated proteins FSP27/CIDEC and LSDP5, regulated directly by PPARγ and PPARα, are associated with hepatic steatosis and insulin sensitivity." (PMID 26770990, 2016). "Cell death-inducing DFFA-like effector c (CIDEC, also known as Fsp27) has emerged as an important regulator of metabolism associated with lipodystrophy, diabetes, and hepatic steatosis." (PMID 26189824, 2015). "As a member of the CIDE family, FSP27/CIDEC plays important roles in hepatic steatosis." (PMID 26770990, 2016). "Overall, CIDEC gene is a novel regulator of obesity, type 2 diabetes, and liver steatosis." (PMID 26189824, 2015). "Notably, Fsp27 deficient mice have a healthy metabolic profile but when challenged by substantial energetic stress, they acquire features found in the CIDEC E186X patient, such as insulin resistance and hepatic steatosis." (PMID 37079518, 2023). "ACC, FASN, PPARG, CIDEC, and especially CIDEA are all involved in the onset of hepatic steatosis and lipid droplet fusion in MASLD." (PMID 39958875, 2024). "In contrast, network members promoting development of hepatic steatosis, such as PPARγ, SCD, SREBF1, ACOX1, CIDEC and CFD (adipsin) are repressed during early phase and induced during the late phase of hepatic response to HF diets." (PMID 19680557, 2009). "Fat-specific protein 27 (FSP27)/cell death-inducing DFF45-like effector-C (CIDEC) and lipid storage droplet protein 5 (LSDP5), two members of the LDAP family of proteins, have been shown to facilitate liver steatosis and regulate insulin sensitivity." (PMID 26770990, 2016).
Obesity (23 papers, 2008 to 2025). Accumulation of substantial excess body fat. "In our study, we have discovered a mechanistic respect of obesity-driven AAA formation that is mediated by CIDEC/FSP27, an LD-associated protein mainly expressed in adipocytes, acting as a pivotal regulator of aortic inflammation and vascular remodeling." (PMID 39872985, 2025). "Given that CIDEC/FSP27 is implicated in lipid storage and adipose tissue expansion, we hypothesize that it may play a role in the development of obesity-related AAA." (PMID 39872985, 2025). "Our findings expand our knowledge of the role of PVAT in AAA and highlight the potential of CIDEC/FSP27 as a therapeutic target for obesity-related AAA." (PMID 39872985, 2025). "We next investigated the role of CIDEC/FSP27 in the development of AAA triggered by HFD-induced obesity." (PMID 39872985, 2025). "In summary, our findings identify human CIDEC as a potential ‘drug’ or a ‘druggable’ target to reverse obesity-induced lipotoxicity and glucose intolerance." (PMID 35963433, 2022). "In human liver samples of individuals with obesity and diabetes mellitus, CIDEC was significantly upregulated." (PMID 33897762, 2021). "Overall, our study demonstrates that CIDEC/FSP27 in adipose tissue contributes to obesity-related AAA formation, at least in part, by enhancing PVAT inflammation and macrophage infiltration, thus shedding light on its significance as a key regulator in the context of obesity-related AAA." (PMID 39872985, 2025). "CIDEC, or Fsp27, is one of three members of the CIDE-family (cell death-inducing DFF45-like effector) which is important in regulation of energy homeostasis and also linked to development of different metabolic disorders like obesity and diabetes." (PMID 28038473, 2017). "Moreover, FSP27/CIDEC-null mice are resistant to diet-induced obesity and insulin resistance, and exposure of primary rat hepatocytes to free fatty acids (FFAs) increases LSDP5 expression and lipid accumulation." (PMID 26770990, 2016). "On day 4, the network showed inhibition of the upstream regulator N-CoR in BPS-treated cells which leads to activation of adipogenic genes such as SCD, PLIN1, ACACB, CIDEC, ADIPOQ and FABP, leading to obesity." (PMID 27685785, 2016). "Pioglitazone significantly (P<0.05) enhanced the mRNA expressions of CIDEC and PPAR-γ in late phase of obesity." (PMID 25210844, 2014). "Cell death-inducing DFFA-like effector C (CIDEC), a member of the CIDE family, is closely related to obesity." (PMID 25210844, 2014). "FSP27/CIDEC is dramatically upregulated in the livers of ob/ob and mice with HFD-induced obesity." (PMID 26770990, 2016). "Increased expression of CIDEC has been demonstrated in adipogenesis, however the role of CIDEC in adipolysis and insulin resistance in the late phase of obesity has not yet been fully discovered." (PMID 25210844, 2014).
Insulin resistance (14 papers, 2013 to 2026). Increased resistance towards insulin, that is, diminished effectiveness of insulin in reducing blood glucose levels. "CIDEC is a key factor in insulin resistance, and its silencing has been linked to the prevention of DN progression." (PMID 38334961, 2024). "Results showed down-regulation of insulin-responsive genes, HK2, EGR1, and CIDEC, which verify insulin resistance through deficiency of insulin signaling." (PMID 32831068, 2020). "Since expressions of insulin-regulated genes are positively correlated with insulin sensitivity, down-regulation of HK2, EGR1, and CIDEC genes in this group possibly verify insulin resistance through deficiency of insulin signaling." (PMID 32831068, 2020). "Interestingly, CIDEC KO mice exhibit higher mitochondrial oxidation and insulin sensitivity, but adipose tissue-specific knockdown causes hepatosteatosis and insulin resistance in HFD-fed mice." (PMID 35963433, 2022). "Finally, to confirm the consequential role of human CIDEC in FA homeostasis and protection against HFD-induced insulin resistance, we generated an innovative adipose tissue-specific mouse model expressing human CIDEC (556G→T) mutation, Ad-CIDECmut." (PMID 35963433, 2022). "A recent study has shown that CIDEC knockdown can ameliorate metabolic abnormalities, insulin resistance, and renal impairment, suppress cell apoptosis and renal fibrosis, and enhance autophagy to prevent DN progression." (PMID 38334961, 2024). "In CFs model of insulin resistance, the expression of CIDEC is increased, accompanied by nuclear translocation of CIDEC (from cytoplasm to nucleus), leading to the inhibition of AMP-activated protein kinase α (AMPK) phosphorylation and further promotes collagen synthesis." (PMID 37065745, 2023).
steatosis (8 papers, 2009 to 2025). Increased lipid within the cytoplasm of cells. "Concomitant with the increase in PPARγ2 expression, overexpressing JMJD2B stimulated the expression of hepatosteatosis genes including fatty acid uptake-associated genes CD36, FABP4 and lipid droplet-associated genes PLIN2, CIDEC in HepG2 cells, which are known PPARγ2 steatosis target genes." (PMID 30214048, 2018). "The genes we identified as steatosis-associated by the network analysis, such as ACOX1, SCD, PPARγ, CFD and CIDEC were re-discovered by the regression analysis." (PMID 19680557, 2009). "Concomitant with reduced PPARγ2 expression, the expression of its steatosis target genes including CD36, FABP4 and PLIN2, CIDEC was also reduced." (PMID 30214048, 2018).
lipodystrophy (7 papers, 2013 to 2026). A congenital or acquired disorder characterized by abnormal loss or redistribution of the adipose tissue in the body. "A nonsense mutation, E186X, in CIDEC, has been associated with lipodystrophy, dyslipidemia, and insulin-resistant type 2 diabetes mellitus (T2DM)." (PMID 39030618, 2024). "Notably, while many previously known lipodystrophy genes fell within the “lipocluster”, several did not (e.g., CAV1, PTRF, AKT2, CIDEC, LMNA)." (PMID 30940487, 2019).
familial partial lipodystrophy (5 papers, 2016 to 2025). "A loss of function mutation in CIDEC causes a familial partial lipodystrophy." (PMID 27835940, 2016). "Partial lipodystrophy syndromes are classified into Familial Partial Lipodystrophy (FPLD) including FPLD1 (Köbberling syndrome), FPLD2 (Dunnigan syndrome, due to mutations in the LMNA gene), FPLD3 (PPARG gene), FPLD4 (PLIN1 gene), FPLD5 (CIDEC gene), FPLD6 (LIPE gene) gene mutations." (PMID 41341138, 2025). "Regarding Familial Partial Lipodystrophy (FPLD), the main subgroups, FPLD2 to 6, are associated with pathogenic variants in LMNA, PPARG, PLIN1, CIDEC and LIPE respectively, whereas FPLD1 is thought to be of polygenic origin." (PMID 38678257, 2024).
hypertriglyceridemia (4 papers, 2017 to 2025). A laboratory test result indicating elevated triglyceride concentration in the blood. "In conclusion, this study has indicated that 3′ UTR variation in CIDEC is associated with the risk of elevated fasting glucose, the progression of hypertriglyceridemia and hypertension, and the efficacy of angiotensin II-targeted antihypertensive agents." (PMID 28415694, 2017). "A known single nucleotide polymorphism in CIDEC produces a nonfunctional protein causing partial lipodystrophy, hypertriglyceridemia, and insulin-resistant type 2 diabetes." (PMID 35963433, 2022).
breast carcinoma (3 papers, 2019 to 2025). "Finally, spots in the fourth cluster coexpress adipocyte markers (ADIPOQ, PLIN1, CIDEC) reflecting adipocyte-rich stroma that lead to microvasculature in breast cancer." (PMID 41249066, 2025). "Up-regulated expression of COL10A1, MMP11, CST1, GJB2, MMP1, MMP13, and CEACAM6; down-regulated expression of ADH1B, CIDEC, THRSP, GPD1, TIMP4, FABP4, and SCARA5 genes was common in breast cancers of the two populations." (PMID 31292488, 2019). "CIDEC has previously been shown to be downregulated in breast cancer but not specifically in TNBC." (PMID 39409999, 2024). "Though CIDEC and CD300LG have been shown to be downregulated in other breast cancers, they have not previously been identified in TNBC." (PMID 39409999, 2024).
hepatocellular carcinoma (3 papers, 2019 to 2023). A malignant tumor that arises from hepatocytes. "Relevant literature studies have revealed that CIDEC is over-expressed in various cancers, such as hepatocellular carcinoma and clear cell renal cell carcinoma." (PMID 37978443, 2023).
alcoholic steatohepatitis (2 papers, 2016 to 2019). "In increased mRNAs, UCP2 was found to participate in hepatic simple steatosis; CIDEC was identified to promote alcoholic steatohepatitis in mice and humans and Acot2 was located at mitochondria matrix and associated with lipid metabolism." (PMID 27677588, 2016). "Interestingly, the role of FSP27/CIDEC has recently been investigated in alcoholic steatohepatitis." (PMID 31097771, 2019).
osteoporosis (2 papers, 2019). A condition of reduced bone mass, with decreased cortical thickness and a decrease in the number and size of the trabeculae of cancellous bone (but normal chemical composition), resulting in increased fracture incidence. "The results implied that mRNA CDKN2B,CIDEC,and THBS4 may play key roles in osteoporosis process and development." (PMID 31164921, 2019).
Type 2 diabetes (2 papers, 2011 to 2015). "CIDEC was also found to be expressed in the steatotic liver of the type-II diabetes model mice." (PMID 26189824, 2015).
alcoholic hepatitis (1 paper, 2019). Acute hepatitis resulting from ingestion of alcohol. "The authors also reported that hepatic expression of CIDEC mRNA increased more than 40-fold in samples from patients with alcoholic hepatitis and correlated with severity of the disease." (PMID 31097771, 2019).
breast tumor (1 paper, 2015). "This is in agreement with the previous findings that AQP7 expression was down-regulated in breast tumor and CIDEA and CIDEC are cell death-inducing DFFA-like effectors to activate apoptosis." (PMID 26618778, 2015).
colitis (1 paper, 2024). Inflammation of the colon. "It was not surprising that the expression levels of CIDEC, NUMA1 and RAG1 in human subjects; Ndrg1 and Pea15a in mice with TNBS-induced colitis; and Cidec, Pea15a and Xbp1 in mice with DSS-induced colitis were not significantly different given the small sample sizes." (PMID 38778086, 2024).
depression (1 paper, 2016). "Among them, the expression levels of CIDEC, RNASE1, SLC36A1, and STYXL1 mRNA were significantly changed depending on the state of depression in the RT-qPCR analysis, which was consistent with the results of the microarray analysis." (PMID 26926397, 2016).
Glucose intolerance (1 paper, 2022). Glucose intolerance (GI) can be defined as dysglycemia that comprises both prediabetes and diabetes. "We performed clinical human and experimental animal model investigations to identify a novel mechanism of CIDEC-mediated regulation of the lipolysis to protect against high-fat diet (HFD)–induced glucose intolerance." (PMID 35963433, 2022).
gout (1 paper, 2021). A condition characterized by painful swelling of the joints, which is caused by deposition of urate crystals. "The final nine surviving monocyte-specific differentially methylated CpG sites were mapped to eight genes (PRKCZ, CIDEC, VDAC1, CPT1A, BIRC2, BRCA1, STK11, and NLRP12) that have not previously been studied in the field of gout genetics." (PMID 33493135, 2021).
keloid (1 paper, 2022). An irregularly shaped, elevated mark on the skin caused by deposits of excessive amounts of collagen during wound healing. "PCR showed that LEP, CIDEC and lncRNA HOTAIR showed increased expression (p < 0.05) in trunk keloid of trunk, while none showed statistical difference in ear keloid." (PMID 35677827, 2022).
lung adenocarcinoma (1 paper, 2019). A carcinoma that arises from the lung and is characterized by the presence of malignant glandular epithelial cells. "Accordingly, CIDEC has opposite roles in cell proliferation and migration to ALR14 in lung adenocarcinoma cells." (PMID 31750299, 2019).
lung carcinoma (1 paper, 2019).
pancreatic cancer (1 paper, 2021). "Among 39 differentially expressed factors, seven up-regulated genes (CAV2, CIDEC, HILPDA, HSD17B11, NCEH1, RAB5A, and SQLE) and two down-regulation genes (BSCL2 and FITM1) were significantly associated with overall survival of pancreatic cancer patients." (PMID 34078402, 2021). "We further identified that enhanced expression of 7 genes namely CAV2, CIDEC, HILPDA, HSD17B11, NCEH1, RAB5A, and SQLE are associated with significantly shorter overall survival whereas elevated expression of BSCL2 and FITM1 correlates with longer overall survival of pancreatic cancer patients." (PMID 34078402, 2021).
sarcoma (1 paper, 2025). A usually aggressive malignant neoplasm of the soft tissue or bone. "Validation using the public Gene Expression Profiling Interactive Analysis 2 sarcoma dataset confirmed consistent PLIN3 upregulation, and down-regulation of DGAT2 and CIDEC in tumor samples, mirroring our GbPDTO findings." (PMID 41376821, 2025).
cancer (9 papers, 2013 to 2024). A tumor composed of atypical neoplastic, often pleomorphic cells that invade other tissues. "CIDEC is negatively regulated by estrogen and is involved in apoptosis in breast tissue, perhaps explaining the specific downregulation in breast tissue despite reports of CIDEC upregulation in cancers of other tissue types." (PMID 39409999, 2024). "The precise and specific role of CIDEC in cancer needs to be clarified." (PMID 34078402, 2021). "However, few studies of CIDEC expression in cancer cells have been reported." (PMID 31750299, 2019). "The six main genes are involved in the cancer and inflammatory processes (YWHAZ, CCL2 and SMPD2) and lipid droplet formation and metabolism (CIDEC, VLDLR and FASN) and significantly increased in NASH patients compared to control or NAFL groups." (PMID 31717414, 2019).
tumor (7 papers, 2017 to 2025). "The expression of CIDEC in tumor tissue was significantly lower than that in adjacent normal tissues, while the expression of EPS8L3 and MUC13 was significantly higher in tumor tissues." (PMID 37978443, 2023). "CIDEC was significantly down-regulated in tumor tissues, while EPS8L3, MUC13 and PLEKHS1 were significantly highly expressed in tumor tissues." (PMID 37978443, 2023). "Among the top dysregulated genes when comparing control and tumor free tissue were those involved in apoptosis (CIDEC, MUC1, ZBTB16, PRNP, ECT2), immune response (IFI27) and differentiation (KRT36)." (PMID 28038473, 2017). "Comparing tumor free tissue with controls showed higher expression of CIDEC, MUC1 and ZBTB16 in the majority of tumor free samples." (PMID 28038473, 2017). "CIDEC, a member of the cell-death-inducing DFF45-like effectors family, is located on human chromosome 3p25, a region associated with a high frequency of loss of heterozygosity in a wide range of tumor tissues." (PMID 31750299, 2019). "Heatmap analysis showed marked upregulation of PLIN3, whereas LIPG, DGAT2, CIDEC, and PLIN1 were down-regulated in tumor tissues and GbPDTOs compared to those in normal tissues." (PMID 41376821, 2025). "IHC further confirmed the differential expression of CIDEC, EPS8L3 and MUC13 in tumor tissues and adjacent normal tissue." (PMID 37978443, 2023). "In addition, RT-PCR results displayed that CIDEC was significantly reduced in tumor tissues, MUC13 was significantly increased in tumor tissues, EPS8L3 showed an up-regulated tendency, while PLEKHS1 was down-regulated in tumor tissues." (PMID 37978443, 2023). "CIDEC, EPS8L3, MLC13 and PLEKHS1 may be potential prognostic factors for STAD and can be used to assess the level of immune cell infiltration in tumour tissues." (PMID 37978443, 2023).
cardiovascular disease (1 paper, 2022). "As the SI-CIDEC-/--HFD mice had lower TG, TC and LDL-C levels than the WT-HFD mice, small intestine-specific knockout of CIDEC may reduce cardiovascular disease risk by improving blood cholesterol composition." (PMID 36263170, 2022).
CIDEC also shares sentences with these, for which no sentence is quoted: diabetes (5 papers); metabolic syndrome (3); clear cell renal cell carcinoma (2); Dunnigan syndrome (2); metabolic disorders (2); acquired lipodystrophy (1); adenoma (1); aneurysm (1); Cirrhosis (1); diabetic cardiomyopathy (1); hyperlipidemia (1); Hypertension (1); hyperuricemia (1); laminopathies (1); multiple lipomatosis (1); neuroblastoma (1); osteoarthritis (1); partial lipodystrophy (1); pheochromocytoma (1); prostate carcinoma (1); retinal angiomas (1); thoracic aortic aneurysms and dissection (1); thyroid cancer (1); tongue squamous cell carcinoma (1); uveal melanoma (1).